SOX2 (SRY-box transcription factor 2)
Diseases named in the same sentence as SOX2 in open-access papers (continued):
Sharing a sentence is not in itself a finding about the gene and the disease.
cancer (continued). "CDK1 has been shown to phosphorylate and regulate distinct functions of several substrates, including disruptor of telomeric silencing 1-like (DOT1L), SRY-box transcription factor 2 (SOX2), and pyruvate dehydrogenase kinase 1 (PDK1), in various cancers." (PMID 40695806, 2025). "CCNA2, SFN, HMGA2, SOX2, and RBP2 have been identified as significant biomarkers for cancer diagnosis and prognosis, particularly in liver cancer." (PMID 40251374, 2025). "YAP1, a transcription factor that induces cancer stemness and is overexpressed in HNSCC, like SOX2, served as a control for efficient and high editing since it caused >50% editing in two different cell lines (UMSCC‐104, FADU)." (PMID 39736115, 2025). "Prior research confirms the presence of SOX2, PIWI proteins, and MALAT1 in plasma of cancer patients, supporting their relevance as non-invasive biomarkers." (PMID 40674376, 2025). "OSMi-mediated inhibition of cancer stem cell phenotypes including mammosphere formation, ALDEFLOUR staining and expression of CSC factors c-Myc and SOX2 were partly reversed in cells containing ITCH knockdown compared to controls." (PMID 40136647, 2025). "Based on the notion of “transcriptional addiction,” targeting transcription regulators, including CDK7, has emerged as a powerful strategy to attenuate cancer dependency, particularly in cancers that rely on SE-driven genes (e.g., MYC, RUNX2, SOX2, SOX9)." (PMID 39800748, 2025). "The ELISA results confirmed the significantly higher plasma concentrations of SOX2, PIWI proteins in cancer patients compared to healthy controls, supporting their elevated expression observed in qRT-PCR analysis." (PMID 40674376, 2025). "MiR-126 alters the biological functions of some genes such as PI3K, EGFL7, HOXA9, sKRAS, CRK, ADAM9, IRS-1, SOX-2, SLC7A5, and VEGF, as well as involves in inflammation, cell migration, angiogenesis, recurrence of cancer, and metastasis." (PMID 38445462, 2024). "In stage I-IV cancer, the positive rates of GBU4-5 (8.3%), MAGE A1 (15.4%), GBU4-5 and SOX2 (both 18.9%), and SOX2 (27.6%) were the highest, respectively." (PMID 38773432, 2024). "Our results indicated that the expression of SOX2, Oct4, Nanog, and CD44 was highly noticeable in these three cancer cell lines, while treatment with hinokitiol effectively reduced the expression of these stemness-related proteins." (PMID 38612715, 2024). "We have identified frequently used markers for the determination of cancer cells and CSCs: Axl, CD44, CD90, CD117, CD276, EGF, PD-L1, PD-1, Sox2." (PMID 38664641, 2024). "SOX2 is a transcription factor belonging to the SOX family that is involved in the proliferation and development of various cancers, demonstrating increased abundance." (PMID 38773432, 2024). "The findings confirmed that RAB4A positively controls levels of NOTCH1 and SOX2, and negatively of NUMB, in these cancer cells." (PMID 39463384, 2024). "These newly uncovered evidence establishes a connection between SOX2/SOX9 gene regulation and TGF-β signaling and identifies the TME as an important factor in promoting treatment resistance in cancer cells expressing SOX2 and/or SOX9." (PMID 38275880, 2024). "This was particularly evident for cancer cells at the border of the invasive areas, which presented higher expression for SOX9 but lower SOX2 expression." (PMID 38275880, 2024). "A loss of XIST in an ovarian cancer cell line leads to an increase in cancer stem cells, as indicated by the expression of cancer stem cell markers such as OCT4 and SOX2." (PMID 38095719, 2024). "Duct-like organoid colonies with extensive stroma mimicking the topology of PDAC, SOX2 and KLF4 transcriptional factors, cancer stem cells’ functionality (CD133 +/CXCR4+ PDAC cells)." (PMID 38791452, 2024). "Shikonin reduced the expression of diverse cancer stem cell markers like ALDH3A1, CD133, EZH2, NANOG, and SOX2." (PMID 38612718, 2024).
cancer (continued). "Hypoxia and HIF1 are generally known to be important in cancer stem cell development, inducing, for example, the expression of OCT4, SOX2, NANOG and Krüppel-like factor 4 (KLF4) as stem cell markers." (PMID 38773108, 2024). "We then validated the levels of NUMB, NOTCH, and SOX2 in a number of RAB4A-high cancer cells (MDA-MB-231, PC3, and SNB19) in response to RAB4A knockdown, and in RAB4A-low cancer cells (MCF7 and H1299) in response to RAB4A over-expression." (PMID 39463384, 2024). "Hence, candidate genes of newly identified gene set signature related to inverse SOX2/SOX9 expression has not only innovative potential to identify cancer cell intrinsic modes of radioresistance but could also potentially predict mechanisms of immune escape during radiotherapy." (PMID 38275880, 2024). "Through activating PI3K/4EBP1 axis, CD44 upregulates SOX2, thereby promoting the CSC properties of the cancer cells." (PMID 38331879, 2024). "It is likely that the impact of SOX2 and SOX9 on the response of cancer cells to irradiation is highly context dependent and critically depends on other epigenetic and genetic alterations." (PMID 38275880, 2024). "Sox2 plays a major role in normal development, but can also drive stemness, EMP and chemoresistance in cancer." (PMID 40994652, 2024). "c-MYC also regulates key transcription factors like SOX2, POU3F2, and OLIG2, driving the reprogramming of cancer stem cells (CSCs) and fueling cancer progression." (PMID 39430761, 2024). "Stem cell-related genes such as SOX2, NANOG, KLF4, OCT4, SNAI2, SNAI1, SOX9, and others are significant promoters of stemness and contribute to increased metastasis in various cancer types." (PMID 38920995, 2024). "HIF1α/HIF2α induce ALKBH5 (alkB homolog 5, RNA demethylase) expression during hypoxic conditions that demethylate Sox2 mRNA (m6A-modified mRNAs), leading to Sox2/CD133 upregulation and maintenance of cancer stem-like traits." (PMID 37922108, 2024). "It is reported that MDSCs activate STAT3 signaling by stimulating the expression of colony stimulating factor 2 (CSF2) in epithelial ovarian cancer, thereby enhancing the transcription of SOX2, NANOG, OCT4a, C-MYC, and KLF4, as well as cancer stemness." (PMID 38561775, 2024). "So far, we have demonstrated that NUMB, NOTCH1, and RAC1 regulate cancer cell self-renewal downstream of RAB4A, and that this signaling chain controls the transcription of SOX2." (PMID 39463384, 2024). "In this study, we obtained pan-cancer and clinical data from TCGA, GTEx, STRING, and TISIDB databases and we analyzed the relationship between SOX2 expression levels and changes in gene diagnostics and survival prognosis." (PMID 38164286, 2024). "Following the administration of 55, the levels of stem cell factors Oct4, Sox2, Nanog, and CD44 were notably reduced, indicating its potential effectiveness as a therapeutic agent against cancer." (PMID 39204369, 2024). "EXOSC5 knockdown diminished EC-CSC self-renewal and reduced expression of key cancer stemness proteins, including c-MYC and SOX2." (PMID 38164180, 2024). "To assess SOX2 expression in LUAD cells, we analyzed the mRNA levels of SOX2 in four LUAD cell lines: A549, H23, H358, and HCC827 using the Cancer Cell Line Encyclopedia (CCLE) through the DepMap portal." (PMID 38334608, 2024). "In this section, we briefly discuss the function of specific stemness factors, such as OCT4, SOX2, and NANOG, which are involved in ROS homeostasis, such as the aryl hydrocarbon receptor (AhR)–Nrf2 axis in cancer development." (PMID 38791215, 2024). "In this study, we examined the expression of the pluripotency genes (NANOG, SOX2, and POU5F1) and the ALDH1A1 gene in ER+ BC tumors across three large cancer datasets." (PMID 38400679, 2024). "First, we measured cancer stem-like phenotype markers, including NANOG, NOTCH, POU5F1(OCT3/4), SOX2, and BMI-1." (PMID 39728923, 2024).
cancer (continued). "The observed increase in Sox2 stability and expression upon modulation of Sox2 acetylation by ACSS2 inhibitor in both normal and cancer in vitro models underscores the significance of our study." (PMID 38473392, 2024). "We evaluated the mRNA levels of typical cancer stem markers, CD44, LGR5, SOX2, and TROY, using qRT-PCR." (PMID 38669046, 2024). "According to RNA-seq data in MCF-7 spheroids, stemness-related genes, such as SOX2 and NANOG, which have been reported to regulate CSC properties in a wide range of cancers, were significantly decreased in siNSDHL compared to siCtrl." (PMID 39516821, 2024). "DPYSL5 overexpression also led to increased mRNA expression of Nanog, SOX2, NSE, CGA, and ASCL1, suggesting that cells achieve characteristic of neuron-like cancer progenitor cells, possibly through the activation of EZH2." (PMID 38238517, 2024). "Accumulating evidence has shown that STAT3 activation plays an important role in the growth and maintenance of GSCs by increasing the expression of major cancer stemness markers, including CD133, Sox2, Oct4, Nanog, ALDH1A1, and integrin α6." (PMID 38474197, 2024). "Among other markers such as Nanog, Sox2, and Oct3/4, CD44 is used extensively to verify that isolated subpopulations of normal or cancer cells have stemness features." (PMID 38791608, 2024). "In cancer stem cells, Myc, Nanog, Oct4, KLF4 and Sox2 are established to be the leading factors for stemness." (PMID 38794128, 2024). "Genes expressed differentially between residual cancer cells and matched pretreatment biopsy specimens from the patient with a pCR (TRG1) treated with nCRT included the known cancer stem cell markers SOX2 and ALDH1A112,13." (PMID 38630793, 2024). "Here, we have identified a list of oscillators that are likely to control cancer progression in GBM and we have experimentally verified the stemness gene SOX2 to oscillate in both proliferative and quiescent GSCs in vitro." (PMID 38267500, 2024). "SIA-IgG reciprocally stimulated SOX2 by activating the c-Met/Akt/Erk signaling axis, constituting a self-propagating loop of SIA-IgG/c-Met/SOX2/SIA-IgG signaling, which is crucial for cancer stemness." (PMID 39194551, 2024). "SOX2 is a pivotal player in both normal physiological processes and cancer progression, particularly as a driver of CSC properties across various cancer types." (PMID 38612911, 2024). "This proliferation coincided with the acquisition of cancer stem cell features, including reduced cell size, enhanced self-renewal capacity, and elevated levels of the cancer stem cell surface marker CD24 and pluripotent transcription factor SOX2." (PMID 38942903, 2024). "We analyzed data of ER+ BC patients from three large cancer datasets to assess the expression of three pluripotency markers (NANOG, SOX‐2, and OCT4), and the stem cell marker ALDH1A1." (PMID 38400679, 2024). "Among the SOX genes, the transcription factors (TFs) SOX2 and SOX9 have been pointed as important players in different types of cancer." (PMID 38275880, 2024). "Western blot results showed higher protein levels of cancer stem cell markers, including SOX-2 and OCT-4, in cancer cells cultured in TaglnOE iMEFs-derived CM, compared to those in the negative control groups." (PMID 36990991, 2023). "The STAT3 inhibitor Stattic significantly reduced sphere formation of cancer stem cells (CSCs) and the expression of OCT4 and SOX2 induced by MDSCs." (PMID 36878933, 2023). "Western blot analysis revealed that SQLE depletion substantially reduced the expression of cancer stemness‐related proteins, including CD44, BMI1, SOX2, and KIF‐4, in ALDHhigh primary HNSCC cells." (PMID 37490552, 2023). "EBA induces apoptosis in BCSC-like populations, as evidenced by a significant increase in cleaved caspase-3 and PARP degradation as well as downregulation of the cancer stem cell markers ALDH1A1, CD49f, Nanog and Sox2 in BCSC-enriched mammospheres." (PMID 37185776, 2023).
cancer (continued). "The expression of EPCAM increases the expression of stemness markers (NANOG, SOX2, and OCT4) in cancer cells, and EPCAM has been described as a marker of cancer stem cells in colorectal, prostate, pancreatic, and breast cancers." (PMID 36674577, 2023). "The relationship between TM4SF1 and cancer stem–related molecules CD44, CD133, OCT4, and SOX2 was detected via qPCR and WB, which confirmed the decrease in the expression of CD44, CD133, OCT4, and SOX2 with the silencing of TM4SF1." (PMID 37069693, 2023). "SOX2 was required in early-stage ADC and SCLC, whereas OCT3, KLF4, and NANOG participate other cancer types." (PMID 36717865, 2023). "We classified the cancer cells into the five cancer subtypes as CDKN2A, SOX2, CXCL1, LAMC2, and proliferating cancer based on the top markers that are highly expressed in each cluster." (PMID 36973297, 2023). "Key regulators of normal and cancer stem cells including the transcriptional factors OCT4, NANOG, and SOX2 were found significantly decreased in KK-LC-1 knockout cells at both mRNA and protein levels." (PMID 37147285, 2023). "Our strategy was to isolate the cancer genes upregulated in the MSC coculture and downregulated in cancer (sox2-KD) when similarly cocultured with MSC." (PMID 37370863, 2023). "The expression of p-CDK1, p-STAT3, CD44, and Sox2 was increased by gemcitabine, while fisetin could reverse the upregulation of these proteins in the combination therapy group, suggesting that inhibition of cancer stemness-related proteins by fisetin enhanced the effects of gemcitabine." (PMID 37743465, 2023). "In particular, the administration of metformin, which has been proposed as a repurposed drug for cancer treatment, alleviates IL-1RA-promoted OSCC malignancy through EGFR/JNK signaling and SOX2 expression." (PMID 37461111, 2023). "It is important for promoting the CSC phenotype, prompting de-differentiation of cancer cells to CSCs, as well as inducing the expression of pluripotent stem cell markers, OCT4, NANOG, SOX2, KLF4, c-MYC." (PMID 37614497, 2023). "NANOG, SOX2, and OCT4 are well-known transcription factors essential for maintaining self-renewal and pluripotency in both normal and cancer stem cells, including BCSC and OCSC." (PMID 37445860, 2023). "Further molecular mechanism found that cancer stemness-related proteins including NANOG, OCT4, SOX2 were dramatically downregulated." (PMID 37149661, 2023). "For the context-depend on partners of p-TEFb including NF-kB in many types of cancer cells, SOX2 and SOX10 in Schwann cells, Mediator both in serval cancer cells and pluripotent stem cells, and c-MYC in pluripotent stem cells." (PMID 36875763, 2023). "COL12A1, ferroptosis markers and cancer stemness markers including GXP4, SLC7A11, Sox2 and Oct4 were obviously weakened by JYQHD." (PMID 37700383, 2023). "Cancer stem cell markers were also examined, which showed an upregulation in ALDH1A3, CD44, and WNT5A in amoeboid cells, and increased SOX2 and BMI1 in escaping cells." (PMID 37575281, 2023). "In acceptor cells, the delivered LSD1 not only promoted cancer stemness by inducing the expression of NANOG, OCT4, SOX2, and CD44 but also produced resistance to oxaliplatin." (PMID 37394580, 2023). "This confirms the repressive effect of NFIB over SOX2 expression and illustrates a potential mechanism upstream of SOX2 that modulates chromatin accessibility at the SRR124–134 cluster and subsequent control of SOX2 transcription in cancer cells." (PMID 37738673, 2023).
cancer (continued). "Expression of SOX2 in BCSC recruits the CD4+ regulatory T cells through secretion of CCL1, where Tregs further promote cancer cell stem properties." (PMID 37445860, 2023). "As a result, the miR-5088-5p inhibitor decreased in IR-induced sphere formation ability by reducing cancer stem-like cell (CSC) marker proteins, such as Oct4, Nanog, Sox2, CD133, and CD44." (PMID 36632615, 2023). "The ‘Yamanaka factors’ OCT3/4, SOX2, KLF4, and c-MYC (OSKM) are essential for maintaining the characteristics of cancer stem cells." (PMID 37762678, 2023). "Because of their adjacent chromosomal localization (3q), SOX2 and TP63 are frequently co-amplified in cancer." (PMID 37046726, 2023). "Experimental inhibition of Sox2, Oct4 or Myc can lead to significant decreases in the CSL phenotypes in cancer cells." (PMID 38203669, 2023). "Targeting c-MET activity, either with small molecule inhibitors or RNA interference, has been shown to suppress the cancer stem-like phenotype by downregulating CSC markers, including CD133, CD44, ABCG2, Sox2, and ALDH1." (PMID 38201226, 2023). "Stem-cell-related factors, such as SOX2, KLF4, NANOG, OCT4, ALDH1, and ALDH2, have been reported to be vital for maintaining cell self-renewal traits in many types of cancer." (PMID 36674577, 2023). "The cell types more abundant in LUSC (SOX2, CDKN2A, proliferating cancer) were placed later in pseudotime than the LUAD-specific cell types (alveolar, pathological alveolar, CXCL1 cancer)." (PMID 36973297, 2023). "Although SOX2 is a well-known marker of (neuronal) stem cell pluripotency, recent research has shown that it also promotes cell migration and invasion in ovarian, breast, retinal, and laryngeal cancers; thus, vitamin D3 in this context may have a broader impact." (PMID 37228489, 2023). "Other cancer stemness-related proteins, including OCT4, SOX2 and SOX9, were also found to be direct transcriptional targets of YAP/TAZ in multiple cancer types." (PMID 37211598, 2023). "MYC is one of the well-characterized transcription factors, including OCT4, SOX2, NANOG, KLF4, in cancer stem cell establishment, maintenance, and functions." (PMID 36941257, 2023). "MUC1-C induces the OCT4, SOX2, KLF4, MYC (OSKM) pluripotency factors in TNBC and other cancer cells." (PMID 37821650, 2023). "SOX2 overexpression in PDAC and other cancer types promotes cancer cell invasion/metastasis, stemness, and drug resistance and is commonly associated with poor survival." (PMID 38012687, 2023). "With the confirmation that the SRR124–134 cluster drives SOX2 overexpression in the BRCA and LUAD cell lines, we investigated chromatin accessibility at this enhancer cluster within primary tumors isolated from cancer patients." (PMID 37738673, 2023). "In the present study, we found that the STAT3 signaling pathway played an important role in mediating the function of IL20RB in promoting cancer stemness and chemoresistance, and IL20RB-STAT3 signaling promoted the expression of NANOG, SOX2 and POU5F1." (PMID 38098005, 2023). "The relative gene expression of the stem cell markers OCT4, SOX2, and NANOG was evaluated to confirm the cancer stem cell features of the CD44+ cells." (PMID 36902135, 2023). "It modulates cancer stem cell stemness and pluripotency by targeting many embryonic transcriptional factors that enhance the oncogenic activity of metastatic cancers, including OCT4, SOX2, NanoG, and KLF4." (PMID 37513415, 2023). "The third cluster of the built PPI network is well represented by transcriptional factors e.g., such as SOX2, NANOG and POU5F1/OCT4, which are considered cancer stem cell (CSC) markers." (PMID 37445716, 2023). "We will discuss below how SOX2, OCT4, KLF4, and c-MYC regulate G1 dynamics in stem cells and cancer cells." (PMID 37760529, 2023).